IL13 (interleukin 13)
Diseases named in the same sentence as IL13 in open-access papers (continued):
Sharing a sentence is not in itself a finding about the gene and the disease.
tumor (continued). "Furthermore, as cytokines can assist tumor progression, targeting IL-4, IL-13, IL-10, TGF-β, and CXCL5 or enhancing IFN-γ and some chemokines (e.g., CCL2, CCL3, CXCL9, CXCL10) may inhibit tumor invasion and metastasis." (PMID 32346605, 2020). "It is not yet established whether MAIT cells are producing IL-13 in tumors, but they are present in the tumor microenvironment and accumulate at tumor margins near epithelial breaches, which is consistent with a response to bacterial antigens." (PMID 32508830, 2020). "For example, the blockade of IL-13 or the elimination of either type II NKT cells or myeloid cells could interrupt this immunosuppressive circuit and restore immunosurveillance, preventing tumor recurrence in a CT26 CRC lung metastasis model." (PMID 33419310, 2020). "The inverse association with lymph node involvement was a result of higher IL13 transcript expression in tumor-adjacent non-cancerous tissue in N1 than N0 CRC patients (3 vs. 0.2, p = 0.028) and a tendency toward its lower expression in tumors from N1 patients (2.2 vs. 9.2, p = 0.158)." (PMID 32512917, 2020). "Overall, although IL-13 production was always found to have a negative impact on the immune response, the consequences of IL-33 or IL-25 on ILC2s in a tumor may vary depending on organs or on the cellular and molecular environment." (PMID 31024531, 2019). "In addition, the mRNAlevels of IL-4, IL-10, and IL-13 were significantly higher in the tumor tissues whencompared to nontumor muscular tissues (Ps < .05)." (PMID 29950152, 2018). "In our studies, we observed that CHI3L1, but not IL13, mediated IL‐13Rα2 activation which promoted tumor invasiveness, suggesting that these two ligands might promote differential signaling through IL‐13Rα2." (PMID 30094958, 2018). "To characterize the mutation status and gene expression levels of the cytokines IL-4 and IL-13, their receptors IL-4Rα, IL-13Rα1/2, and the oncogenes c-Met and EGFR, we performed exome and RNA-seq analysis on DIPG tissues (38 tumor exome, 26 normal exome, 28 tumor RNA, 18 normal RNA)." (PMID 29621254, 2018). "Briefly, during the experiment, dCAR-T cells could release significant levels of cytokines only in the presence of cognate tumor cells expressing both CEA and MSLN, including 751 pg/mL IL-2, 9297 pg/mL IFNγ, 1777 pg/mL TNFα, 732 pg/mL IL-4, 8991 pg/mL IL-13, and 99 pg/mL IL-15." (PMID 30103775, 2018). "For instance, work in a spontaneous mammary tumor model showed that IL-4/IL-13-activated TAMs, when exposed to tumor-derived colony-stimulating factor-1 (CSF-1), produce epidermal growth factor (EGF), which in turn promotes motility and intravasation of EGF receptor (EGFR)-expressing tumor cells." (PMID 30355585, 2018). "On the other hand, these results indicate that tumor-derived oxysterols may shape the TME inducing a pro-tumor milieu, as confirmed by the detection in the TME of Mock-4T1 tumors of higher levels of the type-2 cytokine transcripts Il4, Il13, as well as the anti-inflammatory Il10 transcripts." (PMID 30333826, 2018). "Furthermore, using BM chimeric mice, we were additionally able to show that mice lacking IL-13 only in the IELs (WT→IL-13−/−) were as susceptible to DMBA carcinogenesis as mice completely lacking IL-13 and both mutants developed more tumours than WT." (PMID 27357235, 2016). "However, not all NK cells control tumor growth, as certain subpopulations of NK cells can also suppress tumor immunity by producing immune suppressive cytokines (e.g., IL-10, IL-13) and promoting the growth of regulatory T cells (Tregs)." (PMID 29061951, 2015). "However, levels of IL-1α, IL-4, IL-10, IL-13, and TNFα were not significantly altered by tumor growth." (PMID 26347589, 2015).
tumor (continued). "In addition other signals are necessary to MDSCs activation, including IFN-γ, ligands for Toll-like receptors (TLRs), IL-4, IL-13, and TGF-β, produced mainly by activated T cells and tumor stromal cells after induction by different bacterial and viral products, or as a result of tumor-cell death." (PMID 26161414, 2015). "However, in previous studies, we demonstrated that higher binding affinity of IL-13-PE to tumor cells did not enhance cytotoxicity to cells because internalization of only few molecules of IL-13-PE was enough to kill the cells." (PMID 23421960, 2013). "Expression levels of interleukin-13 (IL-13), leptin, lymphotoxin β receptor (LTbR), and macrophage inflammatory protein 1β (MTP1β) were significantly higher and expression level of IL-11Rα was lower for tumor-positive nodes as compared with tumor-negative SN." (PMID 24212647, 2011). "Thus, the systemic but not local delivery of IL13-PE led to the development of a neutralizing antibody response, which inhibited the in vitro toxicity of IL13-PE in IL-13-responsive tumor cells." (PMID 20090941, 2010). "Systemic but not local IL13-PE dosing led to the development of neutralizing antibodies against this chimeric protein, which effectively blocked the cytotoxic action of IL13-PE in vitro toward tumor cells." (PMID 20090941, 2010). "Given that this tumor-inhibitory role could be compromised by antagonistic Th2 (IL13, IL4) and TGFB pathways, we hypothesized that tumours exhibiting simultaneous high Th1 and low TGFB activity may exhibit a better prognosis than tumors stratified by each pathway alone." (PMID 21050467, 2010). "Interestingly, we also observed correlations between pathways (IL12, IFNG, IL2) involved in Th1 mediated immune response, as well as correlations between pathways (IL13, TGFB) that act via Th2 immune responses to putatively suppress the tumor inhibitory role of Th1 pathways." (PMID 21050467, 2010). "However, future additional experimental validation of CSF2 and its regulation, as well as proper exclusion of IL-13 and TSLP in the effects of NCTD on CRC or other types of tumor cells may provide further insights into the particular anticancer mechanism of NCTD." (PMID 40394236, 2025). "To understand whether the macrophage mode of activation changes the effects they exert on the tumor cells, we activated RAW 264.7 macrophages for 24 h as M0 (no treatment), M1 (incubation with 100 U/mL IFNγ and 100 ng/mL LPS) or M2 (incubation with IL-4 and IL-13, 20 ng/mL each)." (PMID 36979746, 2023). "Another 511 ESCC patients tumor tissues from three different centers including Northern and Southern areas of China (validation sets) were collected to confirm whether CD68 and IL-13 based model had popular prognostic priority in patients from different areas or not." (PMID 26771842, 2016). "This is consistent with a study recently published by our group establishing that locoregional delivery of IL13-BBζ CAR T cells, in the absence of lymphodepletion, can reshape the tumor microenvironment and elicit endogenous antitumor immune responses." (PMID 36968221, 2023). "In 1,4-dihydroxy quininib treated UM explants, a significant negative correlation was observed between IL-13 secretion and tumour thickness; IL-1β secretion and tumour dimensions (LUD and LUH); IL-8 secretion and tumour dimensions; and TNF-α secretion and LUH." (PMID 36698840, 2022). "Following treatment with 1,4-dihydroxy quininib, significant increases in secretion of IL-13, IL-2 and TNF-α are observed in the primary tumour explants, but not in the UM cell lines." (PMID 36698840, 2022). "We browsed the GEPIA database and observed low IL-13 expression in 483 LUAD and 486 LUSC tumor specimens, compared with 347 LUAD and 338 LUSC nontumor specimens." (PMID 33569004, 2020).
tumor (continued). "Other cytokines analyzed (GM-CSF, IL-2, IL-4, IL-10, IL-12 (p70), IL-13, IL-17, VEGF and TNFα) were below detection level of the assay, or did not exhibit any significant changes upon tumor growth or Delta24-RGD treatment (results not shown)." (PMID 24866126, 2014). "Pancreatic cancers in situ were not sensitive to IL-13-PE as they do not naturally express IL-13Rα2 and TSA or SAHA alone showed only modest to moderate anti-tumor effects." (PMID 21477288, 2011). "Similar to what was observed in Braf/Pten tumor-draining ILNs, MC903 treatment–promoted GATA3+ Tregs in Braf ELNs exhibited signature expression of ST2, OX40, and PD-1, but not IL-4 and IL-13 which were only detected in GATA3+ Th2 cells." (PMID 36107619, 2022). "In addition, IL4 expression in ILC2s obtained from tumor tissues was higher than NSCLC PBMCs, while there was no distinction in IL13 expression between these two groups." (PMID 34194433, 2021). "Hence, both Ccl2 and Il13 are sufficient to elicit MYC-HCC to metastasize, even if Twist1 is not expressed in the tumor cells." (PMID 31933479, 2020). "However, it is unlikely that T helper cells provide IL-13 upon TPA stimulation, as studies analyzing the role of T helper cells in two-step carcinogenesis have shown that they are tumor-promoting rather than protective." (PMID 24403255, 2013). "IL-2 and IL-13 were not correlated with PR status, whereas IL-1β, IL-6, IL-8, IL-10, IFN-γ, MCP-1, MIP-1β, TNF-α and, to a lesser extent, IL-4, IL-12 and G-CSF were more abundant in PR-negative tumours than in PR-positive ones." (PMID 17261184, 2007). "Consequently, whether or not the MDSC activation is mediated by IL-13 from type II NKT cells, neutralizing TGF-β could interrupt autocrine and paracrine TGF-β loops driving suppression of tumor immunity." (PMID 25389427, 2014). "Interestingly, this IL-13 and a following production of IgE is dependent on engagement of NKG2D on the IELs, perhaps suggesting that the tumor-suppressive effect of NKG2D and skin-resident IELs may not solely be via cytotoxic/type 1-mediated immune surveillance mechanisms." (PMID 25101088, 2014).
infection (713 papers, 2006 to 2026). The state of being infected such as from the introduction of a foreign agent such as serum, vaccine, antigenic substance or organism. "Administration of IL-13 protected mice from CDI-induced weight loss and severe disease, while anti-IL-13 exacerbated infection outcomes." (PMID 40591723, 2025). "IL-13, an inflammatory cytokine, enhances immune cell recruitment at the site of infection during IAV infection and has been linked to increased susceptibility to secondary infections." (PMID 41303479, 2025). "We found that adjuvanting QIV with AddaVax resulted in a type 2-skewed host response to infection, with hallmark type 2 cytokines IL-4, IL-5, and IL-13 present in the lung homogenates of the aQIV group at 5 days post-infection." (PMID 39975920, 2025). "The inability of the WT mice to control the infection was associated with antigen-specific Th2-type responses with higher levels of IgG1, IL-4, IL-13, and total IgE, reduced NO production, and increased arginase activity." (PMID 38392907, 2024). "In another study, a lower Th1/Th2 ratio and higher cytokine response ratios of IL-5 and IL-13 were found to be significantly associated with an increased risk of infections during maintenance therapy in MM patients." (PMID 39559703, 2024). "Minimally overlapping biomarker distributions were observed between EcoHIV-infected and sham mice, with distribution along the PC2 axis corresponding with EcoHIV infection status (EcoHIV was associated with High IL-13, sham was associated with High IL-7)." (PMID 38786105, 2024). "Th2 cytokines (IL-4, IL-5 and IL-13) were only associated with infection intensity in the oldest age group aged 14–18 years of age." (PMID 39250522, 2024). "For infection with N. brasiliensis, we tested mice doubly deficient in Il4 and Il13 and confirmed a causal role of IL-4 and/or IL-13 in inhibition of both Th1 and Th17 differentiation in vivo after MINCLE-dependent immunization." (PMID 36753434, 2023). "After the onset of oviposition following challenge infection, fibrosis-associated genes (il-4, il-13 and acta-2) are increasingly expressed." (PMID 36923416, 2023). "In the infection caused by C. neoformans, the increased production of the type 2 cytokine IL-13 increased lung fungal burden and reduced mouse survival." (PMID 37888224, 2023). "In hepatic iNKT cells IL-13 production during infection was linked to GATA-3+T-bet+ CD4+ and CD4- subsets while IL-4 and IFN-γ was produced by GATA-3+T-bet+ as well as GATA-3-Tbet+/- cells." (PMID 36159876, 2022). "In the small intestine, tuft cells are present in small numbers during homeostasis, but their prevalence increases rapidly upon infection with various Th2-associated pathogens in a manner dependent upon ILC2-derived IL-13 and tuft cell-derived IL-25." (PMID 36073526, 2022). "IL-13-dependent canonical pathway analysis showed a down-regulation (blue) in pathways relating to protein synthesis and cellular stress after infection, with 71% of endoplasmic reticulum stress pathway-associated proteins being regulated by IL-13." (PMID 34127548, 2021). "Further stratification by gene polymorphisms indicated higher infection prevalences among pupils with the IL13-1055C/C or IL13-1055C/T; the IL13-591A/A or IL13591A/G; and the IL13-1258A/A or IL131258A/G genotypes, especially for the 12-14-year age category." (PMID 34185775, 2021). "The IL-4Rα pathway, a common receptor for IL-4 and IL-13 signaling, is essential in generating anti-inflammatory responses and mediating susceptibility to infection by Leishmania parasites causing CL in mice." (PMID 35154068, 2021). "With regard to STH infections, higher infection prevalences were realized among pupils with the IL13-1055C, IL13-591A, and the IL13-1258A alleles." (PMID 34185775, 2021). "Mice were susceptible to the challenge infection despite the development of a Th2 phenotype with elevated levels of IL-4 and IL-13 gene expression but low levels of endogenous expression of IL-25." (PMID 33276813, 2020).
infection (continued). "The inability of mice to produce IL-25 in response to primary infection and, consequently, IL-13 results in susceptibility to infection." (PMID 33276813, 2020). "Considering that type-2 immunity has been associated with resistance to infection by gastrointestinal nematodes, we next analyzed the gene expression of classical Th2 cytokines IL-4, IL-5, IL-13." (PMID 31862904, 2019). "In resistant mice, IL-13 also induces goblet cell hyperplasia and elevated Muc2 and Muc5ac mucins, with deficiency of these mucins causing susceptibility to infection." (PMID 31730667, 2019). "IL-13 increases susceptibility to infection as well as severity by driving increased inflammation and bacterial manifestation." (PMID 30759882, 2019). "A recent review of intestinal helminth infection also showed redundancy between IL-4 and IL-13, indicating that IL-13 deficiency can be compensated for by IL-4 in murine models of infection." (PMID 30759882, 2019). "Overall infection with the L6 lineage was associated with greater increases of cytokines with anti-inflammatory (IL-1RA and IL-13) or Th2-like activity (IL-13 and CCL11)." (PMID 29813061, 2018). "By analyzing the signaling pathways of IL-4/IL-13, which are related to the susceptibility to infection, we noticed shared components with the IGF-I pathway." (PMID 30150896, 2018). "In contrast, during infection, the opposite relationship was frequently found, with IL-4, IL-13, CCL5, CCL20 and CCL24 levels associated with less severe reductions in both FVC and FEV1." (PMID 30463560, 2018). "A lower Th1/Th2 ratio and higher cytokine response ratios for IL5 and IL13 during maintenance therapy were also significantly associated with increased risk for infection." (PMID 29051761, 2017). "By contrast, the Th2 response with high production of IL-4 and IL-13 is associated with susceptibility to infection." (PMID 28567039, 2017). "The production of IL-4 and IL-13 was higher in spleen cells of infected Ebi3-deficient mice on day 7 post-infection, which probably generated an ideal microenvironment required to the differentiation of alternatively activated macrophages." (PMID 29033934, 2017). "At day 21 post infection we observed equivalent infection rates between Setd7f/f and Setd7ΔIEC mice, which was associated with equivalent expression of Ifng and Il13 in the intestine." (PMID 27598373, 2016). "Surprisingly, CD25+ cell-depletion prior to infection caused a shift in the immune response towards Th2, as shown by an increase in the levels of IL-13+ CD4+ T cells and a slight decrease in IFN-γ+ CD4+ T cells in the LRNs." (PMID 27175511, 2016). "To confirm this T helper phenotype, we performed intracellular cytokine staining (ICS) for Th1 (IFN-γ), Th2 (IL-13), Th17 (IL-17A) and Treg (IL-10) associated cytokines in polyclonally stimulated lung leukocytes on day 7 post-infection." (PMID 27683080, 2016). "M3R deficient mice are highly susceptible to secondary infection, with a 4-fold higher recovery of parasites on day 2 p.i., lower levels of IL-4 and IL-13 in the lungs and reduced goblet cell hyperplasia in the airways." (PMID 25629518, 2015). "Systemic TH2 cytokines were positively associated to infection intensity only in the oldest age group (IL-4: r = 0.488, p = 0.008; IL-5: r = 0.400, p = 0.027; IL-13: r = 0.497, p = 0.007)." (PMID 25799270, 2015). "Another study in Mali revealed an association between a single-nucleotide polymorphism in the STAT6 gene at 12q13.3 and intensity of infection by S. haematobium; this polymorphism had an additive effect with IL13 −1055." (PMID 26540410, 2015). "The induction of prototypical Th2 response with high IL-4, IL-5 and IL-13 secretion has long been considered to be the hallmark of active infection in human LF." (PMID 24498448, 2014). "Failure to resolve infection was associated with reduced production of Th2 cytokines, particularly IL-13 and IL-4, abrogated humoral immunity and failure to expand the memory CD4+ T cell compartment." (PMID 24516382, 2014).